PKMP3 (pyruvate kinase M1/2 pseudogene 3)
Gene: Transcribed processed pseudogene on chromosome 6 (85,659,892 to 85,660,606, reverse strand). Ensembl gene ENSG00000220563.
Diseases named in the same sentence as PKMP3 in open-access papers:
PKMP3 is named in the same sentence as 1 disease in open-access papers, as found by Europe PMC text mining. Sharing a sentence is not in itself a finding about the gene and the disease. The quoted sentences say what the papers report.
glioma (2 papers, 2020 to 2022). A benign or malignant brain and spinal cord tumor that arises from glial cells (astrocytes, oligodendrocytes, ependymal cells). "Pseudogenes PKMP3, AC027612.4, HILS1, RP5-1132H15.3 and HSPB1P1 were identified as prognostic predictors for lower-grade gliomas." (PMID 33378744, 2020).